CYP7A1 (cytochrome P450 family 7 subfamily A member 1)
Diseases named in the same sentence as CYP7A1 in open-access papers (continued):
Sharing a sentence is not in itself a finding about the gene and the disease.
cholestasis (49 papers, 2012 to 2025). Impairment of the bile flow caused by obstruction within the liver, or outside the liver in the bile duct system. "It has been reported that SIRT6 inhibits Cyp7a1 transcription, thereby decreasing bile acid synthesis and alleviating liver injury associated with cholestasis." (PMID 39618181, 2024). "They concluded the alleviating effects of bicyclol for cholestasis was associated with the inhibition of cholesterol 7a-hydroxylase (CYP7A1), which is the rate-limiting enzyme for synthesis of bile acid." (PMID 37719856, 2023). "The results showed that FXR, PPAR, and CYP7a1 are closely related to the occurrence and development of liver metabolic dysfunction and cholestasis caused by ethanol extract of FP (EEFP)." (PMID 36193146, 2022). "Loss of either FXR or SHP alone, or Fxr-/-Shp-/- double knock out mice resulted in cholestasis and liver injury as early as 3 weeks of age, and this dysfunction is linked to the dysregulation of bile acid homeostatic key genes, particularly Cyp7a1." (PMID 31396457, 2019). "Moreover, PM2.5 significantly increased the expression of core genes associated with the biosynthesis (Cyp7a1, Cyp27a1, Baat, and Bacs) and regulation (Shp, Fgfr4) of primary bile acids, suggesting that cholestasis is an important cause of PM2.5 hepatotoxicity." (PMID 39195689, 2024). "As an FXR antagonist, Gly-βMCA and its MCA derivatives induce hepatic CYP7A1 expression, which is an undesirable effect in cholestasis." (PMID 41202881, 2025). "We also found that the administration of recombinant protein FGF19 also reversed vancomycin‐induced cholestasis and fibrosis by suppressing the expression of CYP7A1." (PMID 39680750, 2025). "Our results indicate an association between CYP7A1 rs3808607 and the risk of ICP, and an association of NR2B1 rs11381416 with higher liver function test values in women with pregnancy cholestasis." (PMID 40806580, 2025). "CYP7A1, detected in the liver of the Keap1F/F::RbpjF/F::AlbCre mouse, was lowest amongst the comparisons of mice damaged by cholestasis, being found in less than 50% of the RbpjF/F::AlbCre mice." (PMID 38731931, 2024). "Using the APC-KO mouse model mimicking ß-catenin dependent tumorigenesis, cholestasis was also shown to be mediated by the up-regulation of CYP7A1 and of CYP27A1 which are direct targets of ß-catenin involved in bile acid synthesis." (PMID 39261716, 2024). "In this line, expression of oncogenic ß-catenin in mouse hepatocytes was described to lead to the development of severe cholestasis with alteration of expression of CYP7A1." (PMID 39261716, 2024). "This suggests that SIRT6 reduces bile acid synthesis by inhibiting the expression of CYP7A1, thereby alleviating cholestasis." (PMID 39618181, 2024). "CSA, a well-known inducer of cholestasis, downregulated gene expression of CYP7A1, CYP27A1, BAAT, HNF4A, and INSIG1, while it upregulated ACAT2 and CCL20 gene expression." (PMID 38953992, 2024). "The induction of cholestasis was verified by the gene expression changes in two well‐established cholestasis markers: Abcb11/Bsep, the main apical bile acid exporter, and Cyp7a1/Cyp7, a rate‐limiting enzyme in bile acid synthesis." (PMID 37522754, 2023). "CYP7A1 inhibition reduces bile acid synthesis, bile acid accumulation in the liver tissue, and cholestasis." (PMID 36699093, 2022). "Of note, induction of hepatic ER stress in cholestasis decreases gene expression of Cyp7a1, Fxr, Abcc3 and Abcb11 similar to the pattern observed in our study)." (PMID 35948878, 2022). "As such, identification of Sirt6 as a molecule to inhibit CYP7A1, which decreases protein level of ERRγ, can expand our understanding of BA synthesis and cholestasis." (PMID 32701506, 2020). "As expected, induction of cholestasis by LCA feeding resulted in a significant downregulation of Cyp7a1 and Cyp8b1, the rate limiting enzymes of bile acid synthesis." (PMID 31752395, 2019).
cholestasis (continued). "Dyslipidemia is also a feature of cholestasis since repression of Cyp7a1 expression, an enzyme which catalyzes bile acid synthesis from cholesterol, results in hepatic cholesterol accumulation." (PMID 29795465, 2019). "The level of an important FXR target gene, FGF19, which is essential to the intestine-driven repression of hepatic CYP7A1, was reduced significantly in the serum of patients with cholestasis." (PMID 30504803, 2018). "Continued CYP7A1 activity despite elevated serum bile acids in dogs with cholestasis is counterproductive and suggests a failure of feedback inhibition." (PMID 29324798, 2018). "In rodents, LXRα promotes BA synthesis by inducing the expression of CYP7A1 and can also promote BA detoxification and alleviate cholestasis." (PMID 30105244, 2018). "In accordance with the decrease in FGF19 in patients with cholestasis, BA-synthesized enzymes, including CYP7A1, CYP8B1, and CYP27A1, increased significantly in the liver." (PMID 30504803, 2018). "Gene expression of the rate-limiting enzyme in bile salt synthesis, CYP7A1, was upregulated in the liver of animals with combined steatosis and cholestasis compared to cholestasis alone." (PMID 27535001, 2016). "Cyp7a1 mRNA was more abundant in animals with combined steatosis and cholestasis compared to other experimental groups (p < 0.05)." (PMID 27535001, 2016). "While regulating the rate limiting enzyme cyp7a1 in bile acid biosynthesis is a key compensatory mechanism in many cholestatic systems, cholestasis still results in liver damage even when cyp7a1 was downregulated." (PMID 26101777, 2015). "In children with early- and late-stage cholestasis, SLC10A1 and CYP7A1 were significantly downregulated, suggesting that these two genes contribute to cholestasis in human." (PMID 29177108, 2012). "By increasing the expression of CYP7A1, atorvastatin is able to promote bile acid synthesis, which may be responsible for cholestasis and related symptoms." (PMID 39840096, 2024). "To identify the pathway through which SIRT6 exerts its therapeutic effects in reducing cholestasis, we used N-acetylcysteine (NAC), KEAP1-NRF2-IN-1 (KNI-1), acadesine (AICAR), or adeno-associated virus to knock down Cyp7a1 to treat hepatic Sirt6-deficient mice." (PMID 39618181, 2024). "Interestingly, PSC livers have equivalent levels of hepatic BA compared to normal livers despite frank cholestasis, suggesting that lower Cyp7a1 helps keep bile acids in the liver to a minimum." (PMID 34997170, 2022). "The major mechanism responsible for estrogen-induced cholestasis is the activation of ERa receptor with consequent transcriptional repression of basolateral uptake transporters for BAs such as Slc10a1 (Ntcp), and BA synthetic enzymes such as Cyp7a1 and Cyp8a1." (PMID 35388287, 2022). "However, hepatic Cyp7a1 knockdown significantly relieved BDL-induced cholestasis in Sirt6f/f mice." (PMID 39618181, 2024). "It has been found that BAK can increase serum ALT, TBIL, and TBA and reduce CYP7a1, HMG-CoA, PPARα, and SREBP-2 mRNA expression, resulting in cholestasis hepatotoxicity." (PMID 36193146, 2022). "CYP7A1, which serves as the rate-limiting enzyme in the classical BA synthesis pathway, and CYP8B1 were markedly downregulated in BDL-induced cholestasis." (PMID 32296329, 2020). "In the liver, the expression of the rate-limiting enzyme in bile salt synthesis, cytochrome P450 7a1 (CYP7A1), increased noticeably in IF patients with cholestasis." (PMID 30504803, 2018). "In contrast, enteral CDCA treatment was not effective in preventing cholestasis or upregulation of bile acid transporters, even though it suppressed the key bile acid synthesis gene CYP7A1." (PMID 39282416, 2024). "Additionally, the knockdown of hepatic CYP7A1, which serves as a key enzyme in the classical synthesis pathway for bile acids, significantly alleviated BDL-induced cholestasis and counteracted the adverse effects of Sirt6 deletion." (PMID 39618181, 2024).
cholestasis (continued). "Thus, it alleviates cholestasis by regulating the FXR-FGF15 axis and reducing the expression of CYP7A1 in the liver." (PMID 37764808, 2023). "In this regard, the downregulation of CYP7A1, organic anion transporter 1B1 and SLC10A1 in two donors is compliant with the AOP on drug-induced cholestasis and confirms results previously obtained in spheroid cultures of HepaRG cells and in PHH in long-term 2D-sandwich culture." (PMID 34681664, 2021). "Taken together, these results imply that suppression of bile acid synthesis, vis-à-vis, reduced CYP7A1, is not sufficient to prevent cholestasis but that concurrent NR1H4-mediated activation of hepatobiliary bile acid efflux into the intestine is a primary molecular mechanism." (PMID 41043692, 2025). "Additionally, SIRT6 inhibits the estrogen-related receptor γ (ERRγ)-induced transcription of cholesterol 7 alpha-hydroxylase (CYP7A1), a key enzyme for bile acid synthesis, through deacetylation of ERRγ, thereby potentially attenuating bile acid accumulation and cholestasis." (PMID 39618181, 2024). "Taken together these results imply that suppression of bile acid synthesis, vis-à-vis, reduced CYP7A1 is not sufficient to prevent cholestasis, but that concurrent FXR-mediated activation of hepatobiliary bile acid efflux into the intestine is a primary molecular mechanism." (PMID 39282416, 2024). "Furthermore, it could markedly suppress fibrosis, tumorigenesis, and cholestasis by inhibiting TGF-β signaling, the NF-κB pathway, and CYP7A1 activity." (PMID 32802138, 2020). "Therefore, downregulation of cyp7a1 is not the sole answer to alleviate cholestasis because the outcomes are quite different in the sea lamprey and humans, suggesting that lamprey may possess other anticholestatic agents in the liver." (PMID 26101777, 2015). "As reported for cholestasis, an elevated BA pool acts as an endogenous ligand for FXR activation, a negative feedback regulator of CYP7A1, to restrict de-novo BA synthesis via a JNK-dependent mechanism." (PMID 40681041, 2025). "We did not detect differences in CYP7A1 and SHP mRNA when HepG2-NTCP cells were treated with TβMCA/TCA at a ratio of 2.3 versus 0.7 (similar to the ratio in the liver of animals with cholestasis and combined steatosis and cholestasis, respectively; p > 0.05)." (PMID 27535001, 2016).
atherosclerosis (41 papers, 2009 to 2025). A disease characterized by the build-up of fatty material and calcium deposition in the arterial wall resulting in partial or complete occlusion of the arterial lumen. "CYP7A1 deficiency has been linked to hypercholesteremia and atherosclerosis, while its overexpression reduced cholesterol levels both in serum and liver." (PMID 39695937, 2024). "Some reports of human CYP7A1 gene variants have shown that a reduction of CYP7A1 expression is associated with enhanced atherosclerosis." (PMID 30275434, 2018). "A CYP7A1 polymorphism has also been demonstrated to increase the progression of atherosclerosis in male patients." (PMID 24255670, 2013). "However, association studies link the G allele to increased risk of atherosclerosis or greater lipid levels, which are predicted outcomes of reduced CYP7A1 activity." (PMID 40806580, 2025). "CYP7A1 deficiency causes premature atherosclerosis in humans." (PMID 29101899, 2018). "CYP7A1 is the key regulatory enzyme of bile acid synthesis, plays a crucial role in cholesterol metabolism and has been implicated in genetic susceptibility to atherosclerosis." (PMID 24255670, 2013). "Cyp7a1 has been implicated in genetic susceptibility to atherosclerosis." (PMID 22912762, 2012). "Besides, Qu can also affect the expression of LXRα and ABCA1 through the p38-dependent pathway, proprotein convertase subtilisin/kexin type 9 (PCSK9) pathway, and cholesterol 7 alpha-hydroxylase (CYP7A1) pathway to promote cholesterol efflux and reduce the risk of atherosclerosis." (PMID 32565865, 2020). "Third, in the liver, TMAO could reduce the expression of cytochrome P450 family 7 subfamily A member 1 (CYP7A1), a key enzyme in cholesterol metabolism, which is associated with reduced expression and synthesis of bile acids, decreased bile acid distribution, and increased atherosclerosis." (PMID 39852968, 2024). "These genes are involved in cholesterol metabolism (Abca1, Abcg8, Abcg5, Lpl, Cyp7a1, and Pltp), lipid and atherosclerosis (Abca1, Il1b, Ccl2, and Abcg1), bile secretion (Abcg8, Abcg5, and Cyp7a1), and IL-17 signaling pathway (Ccl7, Il1b, and Ccl2)." (PMID 37301941, 2023). "For example, overexpression of CYP7A1 seems to protect against atherosclerosis by reducing the accumulation of visceral fat among other factors, whereas downregulation of CYP1A2 has been correlated with the progression of HCC." (PMID 34262928, 2021). "FXR protected mice against atherosclerosis by inhibiting the expression of CYP7A1 and CYP8B1 in ApoE−/− mice." (PMID 33401598, 2021). "Transgenic mice overexpressing CYP7A1 were protected from atherosclerosis and liver inflammation and fibrosis." (PMID 34680102, 2021). "In an atherosclerosis ApoE−/− mouse model, whole LB consumption upregulated bile acid synthesis gene Cyp7a1, increased the cecal propionic-acid-producing bacteria proportions, and decreased triglyceridemia and atherosclerosis." (PMID 32825710, 2020). "Over-expression of the CYP7A1 enzyme protects against atherosclerosis and adiponectin improves metabolic syndrome and atherosclerosis." (PMID 32676029, 2020). "The modulation of CYP7A1 gene expression, which is crucial for the prevention and improvement of hyperlipidemia and atherosclerosis, has been reported to improve these conditions in animal models overexpressing CYP7A1." (PMID 32961978, 2020). "Thus, Cyp7a1 might be modulated by different nuclear receptors, resulting in diverse regulation of cholesterol and subsequently varying susceptibilities to gallstones and atherosclerosis." (PMID 19835623, 2009). "The aim of this work was to explore whether the genetic variants (rs2081687, rs9297994, rs10107182, rs10504255, rs1457043, rs8192870, and rs3808607) of the CYP7A1 gene are involved in subclinical atherosclerosis (SA) and plasma lipid levels." (PMID 39207177, 2025).
atherosclerosis (continued). "Dysregulated BA profiles are linked to metabolic disorders including non-alcoholic fatty liver disease (NAFLD), diabetes, and atherosclerosis, with reciprocal crosstalk between inflammation and BA synthesis (e.g., IL-1β-mediated suppression of cholesterol 7α-hydroxylase (CYP7A1))." (PMID 41255527, 2025). "Overexpression of Cyp7a1 in transgenic mice liver reduced cholesterol content in the liver and plasma and prevents atherosclerosis; transgenic mice were resistant to high-fat diet-induced fatty liver, obesity, and insulin resistance, and kept triglyceride, cholesterol, and bile acid homeostasis." (PMID 36594057, 2023). "animalis F1-7, KO, and KF groups downregulated the expression of FGF15 in the intestinal tract of atherosclerosis mice induced by high-fat diet and could effectively improve the expression of CYP7A1 in the liver (p < 0.05)." (PMID 34681423, 2021). "Besides, TMAO suppresses expression of liver bile acid synthetase Cyp7a1 and Cyp27a1 and bile acid transporters, Oatp1, Oatp4, Mrp2, and Ntcp, leading to deranged bile acid-related pathways and promotes atherosclerosis." (PMID 33401598, 2021). "Despite similar reduction on Cyp7a1 and Cyp3a11 hepatic expression, CA and CDCA have a drastically different impact on development of atherosclerosis, plasma and hepatic lipids, BAs composition and intestinal absorption." (PMID 33193099, 2020). "An FXR agonist inhibited the expression of CYP7A1 and CYP8B1 in ApoE-/- mice and protected mice against atherosclerosis." (PMID 30319417, 2018). "The variation of development of atherosclerosis in CTX patients could eventually be explained by the relative expression of CYP3A11 and CYP7A1, but it remains to be proven." (PMID 33193099, 2020).
Obesity (41 papers, 2011 to 2025). Accumulation of substantial excess body fat. "Some studies reported that Cyp7a1 causes a very high bile acid pool but lacks triglycerides so protects against diet-induced obesity." (PMID 34305591, 2021). "Transgenic mice overexpressing CYP7A1 are resistant to high fat diet-induced obesity, fatty liver and diabetes." (PMID 36518674, 2022). "Previous study showed that rats with HFD-induced obesity presented cholesterol accumulation in the liver via inhibiting CYP7A1 gene expression, which remarkably decreased the conversion of cholesterol to bile acids." (PMID 36860444, 2022). "In contrast, Cyp7a1 KO mice are also resistant to HFD-induced obesity, fatty liver, and insulin resistance due to induction of the alternative pathway Cyp27a1 and Cyp7b1 and the resultant increased production of the hydrophilic MCA." (PMID 35614477, 2022). "Transgenic mice overexpressing CYP7A1 has been found to be resistant to high-fat diet-induced obesity, fatty liver, and insulin resistance." (PMID 34950689, 2021). "Transgenic overexpression of Cyp7a1 in mice increases bile acid synthesis, insulin and glucose tolerance, reduces inflammation and protects against HF diet induced obesity and steatosis." (PMID 30405201, 2018). "The overexpression of Cyp7a1 have increased bile acid pool and are resistant to high fat diet-induced insulin resistance and obesity." (PMID 22912762, 2012). "Transgenic mice over-expressing Cyp7a1 are protected from high-fat diet induced obesity, fatty liver and insulin resistance." (PMID 21762485, 2011). "Regarding the other TTP family members (i.e., BRF1 and BRF2), only one study has demonstrated that mice depleted for ZFP36L1 are protected from diet-induced obesity and steatosis via an impaired lipid absorption regulation of Cyp7a1 (cholesterol 7α-hydroxylase) and the bile acid level." (PMID 39941720, 2025). "In the present study, CAO was found to down-regulate the Cyp7a1 gene, which may be partly due to the fact that all reported studies of the anti-obesity effects of Cyp7a1 activation are under conditions of a high-fat diet rather than a normal diet." (PMID 40565139, 2025). "Cyp7a1−/− mice are resistant to diet-induced obesity via a yet-to-be-determined mechanism." (PMID 37566087, 2023). "Importantly, Cyp7a1 is regulated by glucose‐ and insulin‐specific mechanisms and becomes dysregulated with diet‐induced obesity and/or insulin resistance." (PMID 35923133, 2022). "Colesevelam was previously found to suppress ileal Fgf15 expression due to its binding of bile acids, which subsequently derepresses hepatic Cyp7a1 expression via the Fxr–Fgf15–Cyp7a1 axis in a mouse model of high-fat diet-induced obesity, which we confirmed in our microbiome-humanized mice." (PMID 35075592, 2022). "Since TSPYL1 knockdown in hepatic cells resulted in increased CYP1B1 and decreased CYP7A1 expression, we asked whether TSPYL1 expression might be associated with obesity and/or plasma cholesterol concentrations in humans." (PMID 36518674, 2022). "Moreover, mice overexpressing Cyp7A1, a rate-limiting enzyme in bile acid synthesis, are resistant to diet-induced obesity, show elevated systemic metabolism, and express higher levels of fat oxidation genes." (PMID 25505420, 2014). "Thus, hepatic SIRT6 likely inhibits diet-induced obesity by suppressing hepatic CYP7A1." (PMID 37566087, 2023). "In addition, activation of CYP7A1 in the liver leads to the accumulation of secondary BAs in plasma, which may contribute to the hypoglycemic and anti-obesity activities of FA." (PMID 36211528, 2022). "CYP7A1 expression could improve hepatic steatosis and obesity by inhibiting hepatic lipogenesis." (PMID 33281537, 2020). "Therefore, CYP7A1 gene is the most important regulatory gene in cholesterol synthesis pathway and is involved in maintaining cholesterol homeostasis, synthesizing bile acids, and preventing obesity." (PMID 31284674, 2019).